PLD5 (phospholipase D family member 5)
Synonyms: FLJ40773; PLDC
Tractability: Antibody: UniProt predicts a signal peptide or a membrane-spanning region. PROTAC: ubiquitination databases record sites on it.
Gene: Protein-coding gene on chromosome 1 (242,082,986 to 242,524,697, reverse strand). Ensembl gene ENSG00000180287.
Subcellular location: Membrane
Subcellular location (Human Protein Atlas): Mitochondria
Gene Ontology:
Molecular function: catalytic activity
Cellular component: mitochondrion; membrane
Genetic constraint (gnomAD): Loss-of-function variants: 37 observed, 61 expected, observed/expected ratio (o/e) 0.61, 90% interval 0.47 to 0.8. The upper end of that interval is the gene's LOEUF score, 0.8, which puts it in group 3 of 6, group 1 being the genes least tolerant of losing a copy. Missense variants: 510 observed, 656.02 expected, observed/expected ratio (o/e) 0.78, 90% interval 0.72 to 0.84. Synonymous variants: 243 observed, 250.76 expected, observed/expected ratio (o/e) 0.97, 90% interval 0.87 to 1.08.
Homologues: Orthologues: chimpanzee PLD5 (99% identical), macaque PLD5 (99% identical), dog PLD5 (96% identical), rat Pld5 (95% identical), mouse Pld5 (94% identical), pig PLD5 (86% identical), guinea pig PLD5 (84% identical), rabbit PLD5 (71% identical), zebrafish pld5 (46% identical), Drosophila melanogaster Pld3 (29% identical), Caenorhabditis elegans F09G2.8 (27% identical), Drosophila melanogaster CG43345 (26% identical), and 3 more. Paralogues in human: PLD3 (30% identical), PLD4 (28% identical).
Diseases named in the same sentence as PLD5 in open-access papers:
PLD5 is named in the same sentence as 12 diseases in open-access papers, as found by Europe PMC text mining. Sharing a sentence is not in itself a finding about the gene and the disease. The quoted sentences say what the papers report.
prostate carcinoma (5 papers, 2021 to 2024). A carcinoma that arises from epithelial cells of the prostate gland. "miRNA-145-5p upregulates apoptosis and inhibits the migration, invasion, and metastasis of prostate cancer via directing phospholipase D 5 (PLD5) modulation." (PMID 35457012, 2022). "MicroRNA-145 overexpression inhibits neuroblastoma tumorigenesis and Phospholipase D 5 (PLD5) to downregulate cell proliferation and metastasis to mitigate prostate cancer." (PMID 35139769, 2022). "Transfection of PLNCaP and PC-3 cells with pcDNA-PLD5 overexpression (OE) or a combination of miR-145-5p mimics and PLD5 OE plasmid was undertaken to clarify miR-145-5p and PLD5 effects in prostate cancer." (PMID 34238129, 2021). "According to these data, PLD5 silencing negatively affects the migration and growth of prostate cancer." (PMID 34238129, 2021). "For instance, miR-145-5p could inhibit PLD5 resulting in downregulation of cell proliferation and metastasis in prostate cancer." (PMID 34723759, 2021). "Prior prostate cancer studies have also shown miR-145-5p can inhibit cell growth via other targets, including WIP1, PLD5, and SOX2." (PMID 38673886, 2024).
autism spectrum disorder (1 paper, 2022). A spectrum of developmental disorders that includes autism, and Asperger syndrome. "PLD5 is still a poorly understood gene, and seems to be associated to autism spectrum disorder in the first reports." (PMID 36192753, 2022).
dementia (1 paper, 2025). Loss of intellectual abilities interfering with an individual's social and occupational functions. "Lastly, for the neurocognitive outcome RAVLT.learning, the detected causal SNP corresponds to the gene PLD5, which has been associated with incident dementia in genome‐wide analyses, potentially related to incident AD." (PMID 40741986, 2025).
osteosarcoma (1 paper, 2021). A usually aggressive malignant bone-forming mesenchymal neoplasm, predominantly affecting adolescents and young adults. "The outcome indicated that the expression level of ARHGEF3 and PLD5 may have an obvious association with the overall survival of patients with osteosarcoma." (PMID 34350290, 2021). "Survival analysis also indicated that hsa-mir-124 and target mRNAs (ARHGEF3 and PLD5) may have an obvious association with the prognosis of patients with osteosarcoma." (PMID 34350290, 2021).
renal carcinoma (1 paper, 2025). A carcinoma arising from the epithelium of the renal parenchyma or the renal pelvis. "As a critical oncogenic molecule, miR-145 inhibits the proliferation, invasion, and metastasis of prostate, bladder, and renal cancers while inducing apoptosis in tumor cells by targeting and regulating oncogenic signaling pathways, such as PLD5, SWAP70, and STAT3." (PMID 40689207, 2025).
tumor (8 papers, 2013 to 2025). "Further analysis revealed that the miR-145-5p/PLD5 axis inhibits tumor metastasis by regulating epithelial-mesenchymal transition (EMT)-related molecules, such as E-cadherin and N-cadherin." (PMID 40689207, 2025). "The work also offered in vitro and in vivo evidence to understand the effects of increased or decreased miR-145-5p or PLD5 in PCa tumor suppression or progression." (PMID 34238129, 2021). "Our findings agreed with the hypothetical postulation to further elucidate on miR-145-5p tumor inhibition role via modulation of PLD5, whereby co-transfection with miR-145-5p mimics and PLD5OE upregulated proliferation, invasion, and migration of PCa." (PMID 34238129, 2021). "Two other genes of potential relevance to tumor growth, MAP1LC3C (microtubule associated protein 1 light chain 3 gamma) and PLD5 (phospholipase D family, member 5) colocalize to chromosome 1q43." (PMID 23555580, 2013). "By contrast, the 3′ end of PLD5 emerged as an important candidate region for tumor growth in both populations peaking in AA at rs316912 (p = 6×10−4) and in EA at rs1021791 (p = 1.3×10−3)." (PMID 23555580, 2013).
cancer (3 papers, 2013 to 2021). A tumor composed of atypical neoplastic, often pleomorphic cells that invade other tissues. "While the relevance of FH, EXO1, MAP1LC3C and PLD5 functions to the development of cancer is plausible, that of the associated RGS7 is intriguing and deserves comments." (PMID 23555580, 2013). "However, the exact role of PLD5 has not been studied well, especially in cancer." (PMID 34238129, 2021).
brain disorder (1 paper, 2022). A disease affecting the brain or part of the brain. "Further, copy number variations including the PLD5 gene were associated to brain disorders but described also as simply "passenger genes," since its variations were found in normal individuals in the Database of Genomic Variants." (PMID 36192753, 2022).
PLD5 also shares sentences with these, for which no sentence is quoted: Barrett esophagus (1 paper); neuroblastoma (1); Obesity (1); uterine fibroid (1).